ACTR6 (actin related protein 6)
Description:
Required for formation and/or maintenance of proper nucleolar structure and function. Plays a dual role in the regulation of ribosomal DNA (rDNA) transcription (By similarity). In the presence of high glucose, maintains active rDNA transcription through H2A.Z deposition and under glucose starvation, is required for the repression of rDNA transcription, and this function may be independent of H2A.Z (By similarity).
Synonyms: hArp6; CDA12; ARP6; FLJ13433; HSPC281; MSTP136; hARPX
Tractability: Small molecule: a structure with a bound ligand is known. Antibody: the Human Protein Atlas places it where antibodies can reach. PROTAC: ubiquitination databases record sites on it.
Gene: Protein-coding gene on chromosome 12 (100,199,122 to 100,241,865, forward strand). Ensembl gene ENSG00000075089.
Subcellular location: Cytoplasm, cytoskeleton; Nucleus; Nucleus, nucleolus
Subcellular location (Human Protein Atlas): Cytosol; Plasma membrane
Gene Ontology:
Molecular function: protein binding; nucleosome binding
Biological process: nucleolus organization; chromatin remodeling; negative regulation of transcription by RNA polymerase I; positive regulation of transcription by RNA polymerase I; regulation of DNA-templated transcription
Cellular component: nucleolus; nucleus; Swr1 complex; nucleosome; cytoskeleton
Genetic constraint (gnomAD): Loss-of-function variants: 23 observed, 32.03 expected, observed/expected ratio (o/e) 0.72, 90% interval 0.52 to 1.02. The upper end of that interval is the gene's LOEUF score, 1.02, which puts it in group 4 of 6, group 1 being the genes least tolerant of losing a copy. Missense variants: 235 observed, 332.3 expected, observed/expected ratio (o/e) 0.71, 90% interval 0.63 to 0.79. Synonymous variants: 98 observed, 108.73 expected, observed/expected ratio (o/e) 0.9, 90% interval 0.76 to 1.07.
Homologues: Orthologues: chimpanzee ACTR6 (100% identical), dog ACTR6 (100% identical), pig ACTR6 (99% identical), rabbit ACTR6 (99% identical), rat Actr6 (99% identical), guinea pig ACTR6 (98% identical), mouse Actr6 (98% identical), macaque ACTR6 (95% identical), tropical clawed frog actr6 (90% identical), zebrafish actr6 (84% identical), Drosophila melanogaster Arp6 (47% identical), Caenorhabditis elegans arp-6 (38% identical). Paralogues in human: ACTA1 (29% identical), ACTA2 (29% identical), ACTB (29% identical), ACTBL2 (29% identical), ACTC1 (29% identical), ACTG1 (29% identical), ACTG2 (29% identical), ACTR1A (28% identical), ACTR1B (27% identical), ACTR2 (26% identical), ACTRT2 (26% identical), ACTR3 (25% identical), and 14 more.
Diseases named in the same sentence as ACTR6 in open-access papers:
ACTR6 is named in the same sentence as 7 diseases in open-access papers, as found by Europe PMC text mining. Sharing a sentence is not in itself a finding about the gene and the disease. The quoted sentences say what the papers report.
lung carcinoma (3 papers, 2022 to 2024). "Among them, ACTR6 encodes a protein associated with the cell cytoskeleton, and its upregulation has been reported in non‐small cell lung cancer, potentially serving as a prognostic marker for lung cancer." (PMID 38578019, 2024). "ACTR6 can be used as a marker of poor prognosis in lung cancer." (PMID 36077333, 2022).
colorectal cancer (1 paper, 2025). A primary or metastatic malignant neoplasm that affects the colon or rectum. "Additional multivariate analysis showed that ACTR6/ACTL6A may function as separate risk variables for the prognosis of patients with colorectal cancer." (PMID 40130245, 2025).
hepatocellular carcinoma (1 paper, 2025). A malignant tumor that arises from hepatocytes. "We used three separate siRNAs to knock down ACTR6 in Huh7 and HepG2 cells in order to functionally investigate the function of this gene in controlling the development of hepatocellular carcinoma." (PMID 40130245, 2025). "Relationship between ACTR6 expression and clinicopathological features of hepatocellular carcinoma patients." (PMID 40130245, 2025). "It is determined that hepatocellular carcinoma has greater levels of ACTR6 protein expression." (PMID 40130245, 2025).
liver cancer (1 paper, 2025). An epithelial or non-epithelial malignant neoplasm that arises from the liver. "In the future, more in vivo experiments should be done to verify the expression of ACTR6 and further explore the specific mechanism of ACTR6 promoting the cell cycle conversion of liver cancer." (PMID 40130245, 2025). "Further survival analysis showed that the higher the expression of ACTR6 in liver cancer tissues, the shorter the patients’ OS." (PMID 40130245, 2025). "In this study, the ARP gene family was used as a breakthrough point to discuss ACTR6’s transcriptome, genomics, immune infiltration, and prognosis in liver cancer." (PMID 40130245, 2025). "The physiologic roles of ACTR6 in liver cancer cells were investigated using real-time qPCR (RT-qPCR) assays, CCK-8, clone creation, cell cycle, and transwell migration and invasion tests." (PMID 40130245, 2025). "Functionally, knocking down ACTR6 inhibited cell migration and proliferation, produced a G1 cell cycle arrest, and decreased the viability of liver cancer cells." (PMID 40130245, 2025). "We confirmed the significant expression of ACTR6 in liver cancer cells and liver tumor tissues, as well as its impact on the prognosis of liver cancer patients, using cell assays and immunohistochemistry analysis." (PMID 40130245, 2025). "Next, we looked at ACTR6’s involvement in liver cancer in more detail." (PMID 40130245, 2025). "Additionally, tissue chips containing regional liver cancer specimens were used to confirm ACTR6 expression and the clinical impact of prognosis using an immunohistochemistry (IHC) test." (PMID 40130245, 2025). "Immunohistochemistry (IHC) was applied to validate the expression of ACTR6 in liver cancer." (PMID 40130245, 2025). "Finally, to investigate the expression and function of ACTR6 in liver cancer cells, real-time qPCR (RT-qPCR) assays, CCK-8, clone creation, cell cycle, and transwell migration and invasion experiments were carried out." (PMID 40130245, 2025).
salivary gland tumors (1 paper, 2022). "Of note, our NGS panel has routinely identified HMGA2 translocations with diverse downstream partners e.g., HMGA2::PTPRD, HMGA2::WIF1, and HMGA2::ACTR6 in three recent salivary gland tumors (carcinoma ex pleomorphic adenoma) that characteristically harbor HMGA2 rearrangements." (PMID 35798968, 2022).
tumor (1 paper, 2025). "In addition, as early as 2020, a study on non-small cell lung cancer found that ACTR6 affects the progression of the disease by influencing the biology of tumor-associated macrophages (TAM), and served as a potential prognostic marker for lung cancer." (PMID 40130245, 2025). "Nevertheless, increased child-pugh grade, tumor status, surrounding hepatic tissue inflammation, and albumin were not linked to increased expression of ACTR6." (PMID 40130245, 2025).
ACTR6 also shares sentences with these, for which no sentence is quoted: carcinoma (1 paper).